CRP (C-reactive protein)
Diseases named in the same sentence as CRP in open-access papers (continued):
Sharing a sentence is not in itself a finding about the gene and the disease.
cancer (continued). "Therefore, a potential role for CRP in inflammatory conditions such as cancer could be speculated, in which increased CRP production leads to binding of CRP to exposed ligands in damaged cells, thereby increasing tissue injury." (PMID 26504362, 2015). "Markers of the systemic inflammatory response, including C-reactive protein and albumin (combined to form the modified Glasgow Prognostic Score), as well as neutrophil, lymphocyte and platelet counts have been shown to be prognostic of survival in patients with cancer." (PMID 25730322, 2015). "Consequently, it has been difficult to define whether CRP is solely a passive marker or an active player in cancer, or to dissect the exact contribution of CRP in tumorigenesis." (PMID 25025473, 2014). "Interestingly, in cancer patients LPC also correlated negatively with CRP." (PMID 25340546, 2014). "Therefore, the highly recurrent mutation at the CRP-286 SNP site is most likely the result of the selection by cancer development, but not simply due to general properties associated with SNP site or genomic location." (PMID 25025473, 2014). "However, the role of CRP in cancers, including CRC, remains poorly understood." (PMID 24255664, 2013). "Thus, CRP concentration data confirm a correlation between cancer progression and inflammation." (PMID 22963460, 2012). "Analysis of the four most common single nucleotide polymorphisms (SNPs) found in the CRP gene that were associated with increased circulating CRP (95% CI of 58-87% increase) revealed that there was no increase in cancer risk or incidence associated with these SNPs." (PMID 23369448, 2012). "However, in cardiovascular disease, CRP is an established risk factor at levels as low as 0.49 mg l–1, and no such threshold has yet been determined for cancer." (PMID 21081932, 2011). "Additionally, in mice, PPARα activation inhibits inflammatory gene expression by downregulation of acute phase proteins such as C-reactive protein (CRP), fibrinogen, and serum amyloid A (SAA) resulting in reduced hepatic inflammation and risk for cardiovascular disease and cancer." (PMID 20847941, 2010). "However, it has been reported that the preoperative, but not the immediate postoperative, elevated C-reactive protein concentrations are associated with cancer-specific survival." (PMID 19319134, 2009). "However, an elevated C-reactive protein concentration (>10 mg l−1) was seen in only 12% of patients, a proportion lower than previously seen in both primary operable disease (approximately 20–40%) and in advanced cancer (approximately 40–80%)." (PMID 17375036, 2007). "Therefore, the CRP level represents no tumor marker, but an important biomarker for monitoring response to treatment of a cancer-related disease trait (tumor-related inflammation): A CRP decrease indicates the control of an either tumor-related or probably tumor-unrelated inflammatory process." (PMID 19690640, 2007). "On multivariate analysis of these significant factors, stratified by stage, only C-reactive protein (HR 2.89, 95% CI 1.42–5.91, P=0.004) and no adjuvant therapy (HR 0.29, 95% CI (0.14–0.62, P=0.001) was independently associated with poorer cancer-specific survival." (PMID 17024120, 2006). "In addition, CRP levels were higher in those patients with a history of cancer." (PMID 15569387, 2004). "Therefore, if in cancer patients C-reactive protein was stimulated by factors other than interleukin-6, then it might be expected that the relationship between interleukin-6 and C-reactive protein would be less strong than that in patients with benign disease." (PMID 15505624, 2004). "The C-reactive protein-albumin-lymphocyte (CALLY) index reflects nutritional, immune, and inflammatory status and has shown prognostic value in other cancers." (PMID 41816341, 2026). "The C-reactive protein-albumin-lymphocyte (CALLY) index reflects the body's inflammatory, nutritional, and immune status, and has been shown to correlate with cancer prognosis." (PMID 42175397, 2026).
cancer (continued). "In BPA-exposed females, IPA suggested cancer as a top disease, and potassium and CRP (C-reactive protein) for clinical chemistry analysis." (PMID 41034487, 2025). "A meta-analysis examining serum inflammatory biomarkers following vitamin D supplementation in cancer patients revealed significant reductions in TNF-α, IL-6, and C-reactive protein (CRP) levels, while IL-10 levels remained unchanged." (PMID 39582404, 2025). "Earlier published studies showed that this approach of CRP and TK1 increase the specificity of cancer detection." (PMID 40351765, 2025). "C-reactive protein (CRP), as a marker of systemic inflammation, holds substantial value in determining the prognosis of cancer patients." (PMID 40133874, 2025). "Elevated circulating inflammatory markers, including C-reactive protein, IL-6, TNF-α, and monocyte chemoattractant protein-1, represent common features of both cardiovascular disease and cancer, reflecting shared systemic inflammatory burden." (PMID 41555998, 2025). "The C-reactive protein (CRP)–albumin–lymphocyte (CALLY) index, an immunonutritional index, has shown prognostic value in various cancers." (PMID 40091005, 2025). "One of the main mechanisms is the excessive production and secretion of cancer-related cytokines, particularly tumor necrosis factor alpha (TNF-α), interleukin-6 (IL-6), interleukin-1 (IL-1), and C-reactive protein (CRP)." (PMID 40862802, 2025). "A study examined the associations between circulating levels of the inflammatory markers IL-6, C-reactive protein (CRP), and TNF-α with overall cancer incidence as well as the incidence of cancers specific to certain sites (breast and prostate)." (PMID 40584290, 2025). "Eight proteins (C-reactive protein, AGRN, XPOT, LDHA, C1QC, ORM1, ANGPTL4, and prostaglandin D2 synthase [PTGDS]) exhibited a continuously upward or downward trend in three or more cancer types." (PMID 39884577, 2025). "CRP, LDH, CA15‐3 and CEA have been widely investigated in veterinary medicine, and numerous novel biomarkers, such as cancer CSCs, CTCs, miRNAs and cfDNA, have been explored for diagnosing CMTs." (PMID 40095734, 2025). "In patients with malignancy, MDW showed the highest AUC (0.864), with PCT and CRP yielding AUCs of 0.819 and 0.792, respectively." (PMID 41303127, 2025). "A clinical cancer study found that, in the acupuncture group, CD3+ T and CD4+ T cell levels increased, while IL-6 and CRP levels decreased." (PMID 40098703, 2025). "WBC, neutrophil counts, platelet counts, CRP, IPR, NLR, PLR, MLR, and SII were higher in the cancer group compared to the control group." (PMID 40362613, 2025). "ECOG PS and CRP and LDH levels were highly prognostic markers throughout disease progression across all cancer entities." (PMID 39885364, 2025). "Our findings, which demonstrate overexpression of CRP in NPC plasma samples compared to healthy controls, further confirm its potential role as a biomarker for this type of cancer." (PMID 40565234, 2025). "The principal finding of this study is that the IPR, a novel inflammation-based biomarker, demonstrated superior diagnostic performance compared to conventional indices such as CRP, NLR, PLR, MLR, and SII in identifying active cancer." (PMID 40362613, 2025). "Novel inflammatory indices (NLR, PLR, LMR) correlate strongly with traditional biomarkers (e.g., CRP, WBC, IL-6) and demonstrate prognostic value in the general population and cancer patients." (PMID 41280395, 2025). "Furthermore, serum C-reactive protein (CRP) levels have been considered as a surrogate of systemic inflammation, which was associated with survival, daily activities, and physical and psychological symptoms in individuals with incurable advanced cancer in palliative care settings." (PMID 41302347, 2025). "Inflammatory and lipid profiles were broadly similar, with mean CRP around 200 mg/L and modestly reduced total and LDL cholesterol, consistent with the nutritional and inflammatory milieu typical of cancer patients." (PMID 41517288, 2025).
cancer (continued). "With regard to proteins released after sonication, several molecules were identified as candidate biomarkers in cancer US supernatants (Beta-2 microglobulin, CA125, CA19-9, CEA, CRP, Galectin-3, TIMP-1, uPA, and VEGF-A)." (PMID 40563629, 2025). "This study aims to evaluate the prognostic value of a new nutritional and inflammatory index, Prognostic Nutritional CRP Ratio (NCR), in patients with cancer cachexia." (PMID 40133874, 2025). "In NHANES 2003–2014 cycles, AA hemoglobin biomarkers were related to an increase in cancer mortality (mediated by low-grade INFLA-score), an inflammatory marker derived from CRP, white blood cell and platelet counts, and granulocyte/lymphocyte ratio." (PMID 40177073, 2025). "A reduction in biomarkers of systemic inflammation, such as ferritin, C-reactive protein, and the inflammatory index Neutrophil/Lymphocyte ratio (NLR), was observed, especially in the LC subgroup of cancer patients treated with Lip." (PMID 40034703, 2025). "Of the 18 variables collected from the electronic medical records, age, sex, BMI, cancer presence, WBC, RBC, serum albumin levels, AST, ALT, ALP, and CRP were included as covariates for propensity score matching." (PMID 39881383, 2025). "After excluding participants with previous cancer diagnosis (except non‐melanoma skin cancer), missing BMI, WHR, WC, and CRP, 429,073 participants remained and were included in the analysis." (PMID 39791283, 2025). "Among the hematological indicators, hemoglobin, prealbumin, GNRI and AGR can reflect the nutritional status, and immunological status of patients with cancer as it was defined by NLR, CRP and LMR." (PMID 40177184, 2025). "This study has constructed a nomogram based on factors such as Malignant tumor, Admission ICU unit, CRP, APTT, Any norepinephrine use, Blood transfusion, Chlorine disinfectant, and Tracheotomy." (PMID 40880363, 2025). "Cancer cachexia is often accompanied by elevated circulating cytokines like IL-6, IL-1β, and TNF-α as well as acute-phase reactants (CRP, fibrinogen) in patients, resulting in a state of chronic systemic inflammation." (PMID 40572244, 2025). "The present study is the second research study using this novel kit and the first-ever in the literature to detect chair-side salivary CRP in OPMD and malignancy patients." (PMID 39851610, 2025). "In the case of CRP, deceased patients with CHF had a trajectory similar to the overall trend, while patients with malignancies had a consistent trajectory from T0 to T1 with a slight decrease from T1 to T2." (PMID 41153844, 2025). "A substantial body of research has been conducted over the years examining the relationship between C-reactive protein (CRP) and malignant tumors." (PMID 39335753, 2024). "The Glasgow Prognostic Score (GPS) and modified GPS (mGPS) are validated risk calculators based on CRP and albumin levels, demonstrated to predict survival in cancer patients, including gastric, lung and renal cancer and for mGPS even in cancer patients independent of tumour site." (PMID 39691271, 2024). "Measurement of systemic biomarker concentrations revealed statistically significant increases (p < 0.05) in all of the following biomarkers in the group of cancer patients relative to controls: blood platelets, NLR, PLR, SII, CRP, IL-6, IL-8, and TNFα." (PMID 38744744, 2024). "Immunepotent CRP (ICRP), a bovine dialyzable leukocyte extract, is an immunotherapy reported to exhibit immunomodulatory properties and cytotoxicity against several cancer cell lines." (PMID 39063180, 2024). "Alongside the increase in C-reactive protein (CRP), animal models of cancer cachexia also show augmented expression of serum amyloid A, α1-antitrypsin, α1-acid glycoprotein, fibrinogen, and complement factors B and C3." (PMID 39596015, 2024). "The C-reactive protein-albumin-lymphocyte (CALLY) index has been identified as a useful and sensitive predictive tool for stratification in cancers." (PMID 38184747, 2024).
cancer (continued). "In conclusion, PCT outperformed CRP and NLR in diagnosing bacterial infections in febrile patients and proved useful in assessing clinical outcomes and cancer progression in NNLCPs." (PMID 39296886, 2024). "The lymphocyte-to-C-reactive protein (LCR) ratio, an immune-inflammatory marker, shows prognostic potential in various cancers." (PMID 39267838, 2024). "Crucially, biomarkers of systemic inflammation, including CRP, SIPS and mGPS, predict survival in patients with cancer treated with cytotoxic chemotherapy, targeted therapy or immune‐checkpoint inhibitors." (PMID 38404120, 2024). "Increased levels of IL-6 and C-reactive protein (CRP) alongside MMP9 with advancing CRC stages indicate the role of systemic inflammation in modulating the tumor microenvironment and driving cancer progression." (PMID 39664453, 2024). "Immunepotent CRP (ICRP), a bovine dialyzable leukocyte extract, has shown promise in inducing cytotoxicity against various cancer types, including hematological cancers." (PMID 39063180, 2024). "Other scores that aim to predict the outcome of cancer patients like the (modified) Glasgow prognostic score (m)GPS, that is based on simple, readily available blood parameters CRP and albumin, are only validated to assess survival probability at baseline." (PMID 39414641, 2024). "CRP and ALB are vital acute-phase proteins reflecting the body’s nutritional state during systemic inflammatory responses and are pivotal in predicting cancer patient survival." (PMID 39410928, 2024). "Recently, a novel cancer biomarker, the inflammation burden index (IBI), was proposed, which is defined as the product of C-reactive protein multiplied by the neutrophil/lymphocyte ratio." (PMID 38398218, 2024). "The cancer group exhibited a notably higher age (p = 0.005), elevated PSA levels (p = 0.027), and increased CRP levels (p = 0.050) compared to the control group." (PMID 38611064, 2024). "Anyway, the study demonstrated the involvement of PD-1/PD-L1 checkpoint in the immune response in case of cancer since a relationship between CPS and CRP was found." (PMID 39069571, 2024). "In clinical settings, the C-reactive protein (CRP)-to-albumin ratio (CAR) has been investigated as a prognostic marker for diverse diseases, including cancer." (PMID 39330000, 2024). "Nevertheless, in the routine diagnostics of cancer patients the subjective tools (SGA, NRS questionnaires), anthropometric measurements and laboratory parameters (albumin, CRP) are constantly used." (PMID 38790185, 2024). "Prealbumin, albumin, and C-reactive protein (CRP) levels and the upper arm muscle area (UAMA) were measured before and after treatment in children with cancer and compared with the control group to evaluate nutritional status." (PMID 39619813, 2024). "If CRP, IL‐6 and YKL‐40 were combined, the AUC was 0.71 for predicting cancer in the cohort of patients with non‐specific signs and symptoms of cancer." (PMID 36440611, 2023). "It has been shown that complement proteins are also involved in the acute-phase response of cancer to PDT, including MBL-A and mouse C-reactive protein." (PMID 37762219, 2023). "In previous studies, it has been demonstrated that the acute phase reactants, C-reactive protein, the erythrocyte sedimentation rate (ESR), and fibrinogen levels are modified in chronic inflammation and in various types of cancers, including CRC." (PMID 38137862, 2023). "Initial as well as subsequent increases in CRP levels predict future CVD, cancer, and mortality in the general population." (PMID 37019514, 2023). "Clear downregulation of certain proteins (CRP, SAA1) which reflect inflammation and cancer risks was observed." (PMID 36979008, 2023). "In conclusion, our study showed that plasma CRP, IL‐6 and YKL‐40 alone or combined cannot be used to identify patients with cancer." (PMID 36440611, 2023).
cancer (continued). "The indices of laboratory tests of patients with SBP were strongly influenced by the cancer in terms of WBC, Neutrophil, TBil, CRP, FNR, PLR, NLR and CAR." (PMID 37951894, 2023). "Adult cancer patients with COVID-19 infection are at higher risks of mortality if they presented with tachypnea, had a recent chemotherapy, history of CHF, high CRP, and high procalcitonin levels at presentation." (PMID 36701309, 2023). "Further studies are needed before the low‐cost biomarker CRP can be recommended to be used to indicate whether further diagnostic evaluation is needed when patients present with nonspecific signs and symptoms of cancer." (PMID 36440611, 2023). "Multiple studies published in the last few years have demonstrated that different inflammatory variables can serve as prognostic indicators for postoperative outcomes among patients with malignancies, and these indicators include PLR, CRP, NLR and SII." (PMID 37438696, 2023). "Plasma levels of C‐reactive protein (CRP), interleukin‐6 (IL‐6) and YKL‐40 reflect inflammation, and are elevated in patients with cancer." (PMID 36440611, 2023). "Related studies in advanced cancer showed that Infliximab was well tolerated with few toxic effects, and it decreased inflammatory factors including CCL2, IL-6 and serum CRP." (PMID 38201482, 2023). "For example, elevated C-reactive protein (CRP), globulin, and certain cytokines have been used as prognostic tools in patients with cancer." (PMID 37396996, 2023). "Both CRP and LDH were identified as biomarkers for poor cancer prognosis, and increased NTL ratio was often observed in patients with advanced cancers or tumor progression." (PMID 38125944, 2023). "Fifth, since C-reactive protein (CRP) and specific interleukin levels are not registered in the nationwide-based claims data (analyzed data source), we could not reflect these variables as direct parameters of cancer risk." (PMID 37259467, 2023). "Overall, laboratory test variables (CRP, PD‐L1 level, dNLR, ALP, ALB, HGB, and WBC) and tumor characteristics (cancer type, prior liver metastasis, and the number of metastatic sites) are the two major factors for mortality prediction." (PMID 35871390, 2023). "C-reactive protein (CRP) and other combined factors were used in early studies, which has been proved to be prognostic markers in cancer patients." (PMID 37197663, 2023). "After evaluating the predictive value of 13 inflammatory indicators for patient prognosis using the C index, the lymphocyte C-reactive protein ratio (LCR) was selected to elucidate the prognostic and predictive values in patients with stage IV cancer." (PMID 36266627, 2022). "Still, there were significant differences among age, male, cancer diagnosis, pleural fluid location, fever, ESR, CRP, T-SPOT, pleural fluid lymphocyte ratio, and ADA (p < 0.05)." (PMID 36056429, 2022). "Some studies have demonstrated a significantly elevated plasma concentration of C-Reactive Protein (CRP) in response to inflammation, tissue damage, and numerous cancer types." (PMID 36532648, 2022). "Second, for the first time, we analyzed the combined prognostic impact of CRP and LHR in patients with cancer." (PMID 35752767, 2022). "The GPS CRP cut-off value has been adjusted from 1.0 to 0.5 mg/dl for patients in Japan and this modified GPS (mGPS) has been used as the benchmark for cancer cachexia in our previous study." (PMID 35949598, 2022). "The modified Glasgow prognostic score (mGPS) and lymphocyte C-reactive protein score (LCS), these two new and readily available markers of inflammation, were initially shown to have independent prognostic value in cancer patients." (PMID 35865381, 2022). "In fact, emerging evidence has demonstrated the prognostic value of systemic inflammation and immune markers, including neutrophil, lymphocyte, platelet, and C-reactive protein (CRP), in various cancers including HCC." (PMID 35756674, 2022).